IL6 (interleukin 6)
Diseases named in the same sentence as IL6 in open-access papers (continued):
Sharing a sentence is not in itself a finding about the gene and the disease.
Sepsis (continued). "In mice, death of animals infected with F. tularensis appears to result from widespread sepsis and inflammation, and mortality was correlated with the extent of the inflammatory response including release of pro-inflammatory IL-6, an early diagnostic marker of bacterial sepsis." (PMID 26739172, 2016). "Sepsis resulted in cognitive impairments, which was accompanied by selective phenotype loss of PV interneurons and increased gp91phox, 4-hydroxynonenal, malondialdehyde, IL-1β, and IL-6 expressions." (PMID 26416717, 2015). "Interestingly, IL-6 (−174 G/C) polymorphism influenced the immune pathogenesis of sepsis in European populations of trauma." (PMID 26561011, 2015). "Recent studies have reported the association between IL-6-174G/C polymorphism and sepsis." (PMID 25734339, 2015). "It has been shown that increased concentrations of KYN or KYNA, both ligands of AhR, and increased concentrations of TGF-β and IL-6 are risk factors for establishment of an immunoparalysis and for a poor prognosis of patients in early sepsis instead of recovery." (PMID 26881062, 2015). "Among these cytokines, Interleukin-6 (IL-6) is one of the most important members which may be associated with sepsis risk and outcome." (PMID 25734339, 2015). "Currently, vast evidence indicates that certain functional genetic variants, such as those in the genes of TNF-a, IL-6 and other inflammatory-related proteins, may be associated with the susceptibility to sepsis by influencing its inflammatory pathogenesis." (PMID 25888255, 2015). "Therefore, there was only a moderate association between IL-6–174G/C polymorphism and sepsis mortality under the recessive model." (PMID 25734339, 2015). "Therefore, we performed the meta-analysis based on the published papers to clarify the association between IL-6–174G/C polymorphism and sepsis." (PMID 25734339, 2015). "Sequence-specific primer based PCR indicated that eight polymorphic loci IL-1α /-889, IL-1β/-511, IL-1R (pstI 1970), TGF-β/ code 10, TNF-α/-308, TNF-α/-238, IL-6/+565 and IL-10/-1082, out of 22 SNPs are significantly associated with sepsis morbidity and outcome." (PMID 26561011, 2015). "We found that HHH preferentially developed under conditions of excessive inflammation, including hematological diseases such as leukemia, lymphoma, and aplastic anemia and sepsis, and that its onset and severity were associated with pro-inflammatory IL-6 and IL-8, respectively." (PMID 24852692, 2014). "The importance of severe infection for HHH may be validated by the other independent risk factors of sepsis and high IL-6 levels." (PMID 24852692, 2014). "Several studies have reported sensitivity for detection of IL-6 in 75 to 90% of circulating serum in the first 24 hours of infection, with a marked reduction in the diagnostic effectiveness 48 hours after the onset of symptoms and suspected sepsis." (PMID 25614712, 2014). "IL-6 and IL-10 has also been demonstrated to be associated with prognosis of severe sepsis." (PMID 24977412, 2014). "An increase in the IL-6/IL-10 ratio, caused by a decrease in IL-10, has previously been associated to the severity of systemic inflammatory response syndrome in patients with sepsis." (PMID 25415590, 2014). "The causal relationship is not known, but what is known is that vitamin D deficiency is associated with increased IL-6, adverse effects on oxidative stress, and increased endothelial adhesion molecule expression, all of which are relevant in the pathogenesis of sepsis." (PMID 23741318, 2013). "LPS−activated macrophages release proinflammatory cytokines such as TNF-α and IL-6, which could cause inflammatory disorders, sepsis or other liver injuries." (PMID 24143247, 2013). "In addition, this mutation had been associated to occurrence of severe sepsis through important secretion of important amounts of pro-inflammatory cytokines (TNFα and IL-6)." (PMID 24252506, 2013).
Sepsis (continued). "Like that seen in the ApcMin/+ mouse, recent data have suggested that burn injury and sepsis are also characterized by increases in IL-6 levels which, at least in these models, is associated with cardiac inflammation, increased apoptosis, and depressed contractile function." (PMID 23589074, 2013). "This study showed that the IL-6-174 C allele was associated with increased incidence of sepsis." (PMID 24310803, 2013). "The second concerns the importance of including the microbiological identification of the agent in the sepsis definition, since there is evidence that the SNP IL-6-174 may be related to an increased risk of sepsis caused by Gram-positive organisms." (PMID 24310803, 2013). "Therefore a protein-microarray for point-of-care testing that simultaneously quantifies the sepsis associated serum proteins IL-6, IL-8, IL-10, TNF alpha, S-100, PCT, E-Selectin, CRP and Neopterin has been developed." (PMID 22438722, 2012). "IL-6 also has important involvement in many pathogenic inflammatory states: IL-6 levels are elevated and correlate with sepsis severity and mortality and IL-6 has been implicated in the cytokine storm following avian influenza A H5N1 and severe acute respiratory syndrome (SARS) infection." (PMID 22679491, 2012). "In a less severe sepsis model, Trif-deficient mice have reduced cytokine production including TNFα, IL-6, and IL-10 suggesting Trif signaling may contribute to systemic inflammation in a mild form of animal sepsis." (PMID 21977329, 2011). "The inflammatory cytokines associated with sepsis such as Interleukin-6 (IL-6), Interleukin-10 (IL-10) and Interleukin-1β (IL-1β) are found to be correlated with the severity of the disease, the evolution of organ failure as measured by the SOFA score and mortality." (PMID 22035174, 2011). "Sepsis caused by B. pseudomallei is characterized by a markedly proinflammatory cytokine profile; in the current cohort of patients we have demonstrated increased plasma concentrations of IL-6, IL-8 and IL-18 when compared to controls." (PMID 20169062, 2010). "Causative factors might be the release of cytokines during sepsis like IL-6, which has been shown to upregulate TLR4 on human monocytes." (PMID 19371402, 2009). "Moreover, IL-6-deficient mice were highly susceptible to sepsis-induced steatosis and hepatocellular injury." (PMID 19936233, 2009). "However, increased brain IL-6 has been associated with severe cognitive impairments and likely contributes to the cognitive and neuroanatomical long-term consequences of sepsis, such as persistent behavioral deficits and neuronal loss." (PMID 19284588, 2009). "Thus, measuring IL6 at the first day of fever allows to identify a group of patients whith a high risk to develop sepsis or a prolonged episode of fever." (PMID 18321393, 2008). "We aimed to analyze whether IL-6 and IL-8 could define a group of patients at low risk of septicemia." (PMID 18321393, 2008). "In this study, it could also be shown that plasma IL-6 and IL-8 levels can possibly be used to define a group with low risk of septicaemia among children with fever and neutropenia." (PMID 18321393, 2008). "High levels of IL-6 have been associated with severe inflammation and sepsis." (PMID 16569262, 2006). "Therefore, the kidney is particularly susceptible to the effects of CD38 ligation in sepsis and may be a primary source of IL-6 production." (PMID 39568061, 2025). "Importantly, misdiagnosing CRS as sepsis or vice versa can lead to inappropriate treatment strategies, as immunosuppressive therapies such as IL-6 inhibitors and corticosteroids may exacerbate underlying infections." (PMID 41347097, 2025). "Therefore, sepsis is associated to the activation of IL-6 related signaling pathways." (PMID 39891057, 2025).
Sepsis (continued). "Similarly, elevated ACSL4 and PTGS2 in ICU sepsis patients are associated with heightened IL-6, IL-8, procalcitonin, as well as high-sensitivity C-reactive protein, demonstrating strong diagnostic performance for sepsis along with its inflammatory complications." (PMID 41250137, 2025). "Several covariates other than IL-6 levels were significantly associated with the risk of mortality in only one of the groups (non-elderly, number of chronic organ dysfunctions, P = 0.016; elderly, BMI and steroid use prior to sepsis onset, P = 0.027 and 0.002, respectively)." (PMID 39800741, 2025). "This shift toward an IL-10/IL-6 cytokine profile suggests a reprogramming of macrophage responses toward an immunosuppressive phenotype, a pattern that has been previously associated with poor clinical outcomes in burn patients and is characteristic of the immune-paralysis phase observed in sepsis." (PMID 41010852, 2025). "Future cohorts will prospectively measure IL-6 in these children and following outcomes such as number of infections per year, requirement for antibiotic treatment, infection-related hospitalisations, intensive care admissions related to infectious causes, sepsis, and mortality." (PMID 40661891, 2025). "Therefore, this review centered on IL-6 related signaling pathways and the biomarkers to analyze sepsis and sepsis-associated chronic diseases with the aim to guide clinicians in the effective diagnosis and treatment, prediction outcomes, and assessment risk for these diseases." (PMID 39891057, 2025). "Therefore, sTREM-1, IL-6, and lactate should be considered in early sepsis risk assessment, while CRP and PCT may be more beneficial for tracking clinical progression." (PMID 39655134, 2024). "Hypocalcemia often occurs in sepsis patients, and this is associated with a decrease in calcium levels mediated by the calcium-sensitive receptor (CaSR), which regulates calcium homeostasis, in response to pro-inflammatory signals such as IL-1β, IL-6, and others." (PMID 39355841, 2024). "High levels of circulating IL-6 during the acute phase of sepsis are associated with a high risk of mortality, and analgesic treatment could be effective for high responders with excessive immune responses, explaining the reduced mortality observed with meloxicam treatment in PCI sepsis mice." (PMID 39281680, 2024). "Although IL-6 and IL-8 have a protective role by recruiting neutrophils and clearing pneumococcus burden during lung infection, overwhelming responses as in the case of D39-WT and comparable responses in the presence of D39ΔMapZ can also cause imbalance resulting in sepsis." (PMID 36877045, 2023). "During sepsis, the pathogen-associated molecular patterns trigger systemic inflammatory responses, leading to an excess production of proinflammatory cytokines that are responsible for coagulopathy, such as interleukin IL-1β, IL-6, and tumor necrosis factor-α (TNF-α)." (PMID 37219401, 2023). "Moreover, a pre-clinical mechanistic study on mortality in early and late sepsis suggested a pertinent association between IL-6 levels and mortality in the early phase of sepsis; the higher the IL-6 levels, the greater the risk of mortality within 4 days of sepsis induction in mice." (PMID 35885778, 2022). "During sepsis, the pathogen-associated molecular patterns trigger systemic inflammatory responses, leading to an excess production of proinflammatory cytokines that are responsible for coagulopathy, such as interleukin (IL)-1, IL-6, and tumor necrosis factor-α (TNF-α)." (PMID 36431172, 2022). "Indeed, we demonstrated that blood neutrophil count, serum IL-6, and serum IL-8 were the possible clinically correlated parameters of COVID-19 infection, which might be associated with sepsis severity; this is supported by previous observations." (PMID 35406667, 2022).
Sepsis (continued). "Moreover, when plasma samples from patients with sepsis and septic shock were analyzed, this phenomenon was exacerbated showing a clear association with the presence of the ~ 67 kDa accessory protein band, and a marked increase in IL-6 and IL-10." (PMID 36536294, 2022). "In addition, the concentration of the three cytokines associated with sepsis severity (IL-6, IL-1β, and IFNγ) was maintained in NK-depleted mice over an extended duration without any increases in magnitude, suggesting a NK cell-limiting effect on the duration and scope of the cytokine storm." (PMID 35053151, 2021). "Their higher levels of IL-6 and TNFα and damage could increase their susceptibility to sepsis." (PMID 33788832, 2021). "When using progranulin as a biomarker for sepsis and pneumonia, the diagnostic performance of this molecule is comparable to that of procalcitonin, and surpasses the other established biomarkers C-reactive protein and interleukin-6 with regard to sensitivity and specificity." (PMID 34476621, 2021). "IL-6-174 G/C polymorphism might influence the transcriptional activity and lower the inflammatory reaction, it did not get the point that it could influence the development of sepsis nevertheless." (PMID 30782124, 2019). "Thus, whilst haemolysis (as measured by low HPX, reflecting cumulative exposure to haem) and IL-10 are both associated with markers of inflammation (IL-6, TNFα, and G-CSF), IL-10 is most closely associated with raised HO-1 in sepsis patients at the time of admission." (PMID 30046137, 2018). "Thus, plasma IL-6 levels have been associated with higher risk of sepsis, septic shock, and death." (PMID 28247301, 2017). "However, LPS could cause neuroinflammation, hypotension, or sepsis in pathological injury; IL-6-pretreated MSCs could promote osteosarcoma growth, which suggested that IL-6 mediated the recruitment of MSCs to facilitate tumor progression." (PMID 29115993, 2017). "The differences between the doses can be related to the efficacy of the compounds present in babassu mesocarp to regulate the IL-6 production and the expression of receptors that can be associated with cellular migration and with the EE effect on the outcome and survival in experimental sepsis." (PMID 27630733, 2016). "Thus, PCT has better diagnostic accuracy for sepsis than CRP or IL-6." (PMID 25460569, 2014). "Furthermore, IL-6 has also been linked to cardiac dysfunction during sepsis." (PMID 23935245, 2013). "Activation of the α7 nAChR expressed on resident macrophages may suppress the local inflammation by reducing the production of pro-inflammatory cytokines TNF and IL-6, which are closely associated with some inflammatory diseases, including sepsis, rheumatoid arthritis, asthma, and diabetes." (PMID 23840548, 2013). "The main objective of this study was to determine whether early measurements of IL-6 (interleukin-6) and IL-10 plasma concentrations (as markers of initial severity) could improve, in association with mHLA-DR recovery, the prediction of sepsis occurrence in severe trauma patients." (PMID 22431998, 2012). "However, etomidate is also well known to cause hypoaldosteronism; to affect levels of interleukin 6 and 10 and may interfere with circulating lymphocytes levels and pro-inflammatory mediators necessary in sepsis." (PMID 22208901, 2011). "Therefore, we tested the hypothesis that there is an association between sepsis-associated delirium and the inflammatory response reflected by interleukin-6 (IL-6) and C-reactive protein (CRP)." (PMID 18457586, 2008). "This prospective study aimed to evaluate the prognostic value of interleukin-6 (IL-6) measured at ICU admission in patients with sepsis and septic shock." (PMID 42193317, 2026). "Elevated levels of plasma IL-6 (>25 pg./mL) 1-month after sepsis induction were observed in both the CL and CLP groups and also in the CLP-D group to a lesser degree." (PMID 42254349, 2026).
Sepsis (continued). "Serum levels of TLR2, TLR4, TLR9, IL-1β, IL-6, IL-8, IL-10, TNF-α and IFN-γ were quantified by enzyme-linked immunosorbent assay at the time of sepsis diagnosis." (PMID 41846925, 2026). "We found that serum lactate levels in sepsis patients were positively correlated with levels of IL‐6." (PMID 41532698, 2026). "Sepsis is initiated by the host immune response and excessive inflammation, leading to the release of pro‐inflammatory cytokines such as IL‐1β, IL‐6, and TNF‐α." (PMID 41551210, 2026). "As a key sepsis-related inflammatory factor, IL-6 drives M2 macrophage polarization; M2 macrophages then locally secrete catecholamines to activate the β3-adrenergic receptor pathway in adipocytes, further amplifying adipose browning and systemic inflammation." (PMID 41498391, 2026). "Secondly, during sepsis, the release of a vast array of inflammatory mediators—particularly cytokines such as interleukin-1, interleukin-6—prolongs ventricular repolarization." (PMID 41545939, 2026). "JAK inhibitors, such as tofacitinib, baricitinib, and ruxolitinib, selectively inhibit different JAK subtypes and effectively reduce the expression of various cytokines, such as IL-6, which plays a crucial role in sepsis and severe infections." (PMID 41521316, 2026). "Tumor necrosis factor-alpha (TNF-α) and interleukin-6 (IL-6) are key mediators of organ dysfunction in sepsis." (PMID 40558557, 2025). "IL-6 is a significant component of the systemic inflammatory response to infection and correlates with survival of patients with sepsis." (PMID 40661891, 2025). "Previous studies have investigated the elevation and significance of IL-6 in patients with infection and sepsis-related DKA." (PMID 40005437, 2025). "We also confirmed increased renal Il6 production following CD38 ligation in an additional mouse model of sepsis induced by faecal suspension intraperitoneal injection." (PMID 39568061, 2025). "The study authors demonstrated that pro-inflammatory cytokines, namely IL-1b and IL-6, were down-regulated in mice with sepsis-induced ALI by miR-483-5p knockdown." (PMID 40076471, 2025). "Patients with severe SARS-CoV-2 infection had comparable levels of C-reactive protein (CRP), interleukin-6 (IL-6), and most types of leukocytes compared to sepsis patients with different disease etiologies." (PMID 41233786, 2025). "When S100A9 was combined with APACHE II and IL-6 to predict 28-day mortality in sepsis, the AUC of the combined model increased from 0.78 (95% CI 0.73–0.83, p < 0.001) to 0.84 (95% CI 0.80–0.89, p < 0.001), demonstrating improved predictive performance." (PMID 40478888, 2025). "A heatmap plot was created to examine the relationship between IL-6, lung injury, and kidney injury during sepsis." (PMID 39955435, 2025). "Instead, proinflammatory cytokines, tumor necrosis factor-alpha and interleukin-6, were significantly lower in the Sepsis-plus-hypoxia group compared with the Sepsis group at multiple timepoints." (PMID 41422365, 2025). "This review generalized the mechanism of sepsis-related chronic diseases via IL-6 related pathways with the purpose to take rational management for these diseases." (PMID 39891057, 2025). "The proliferation of cytokines such as TNF-α, INF-γ, IL-6, and IL-8 have been identified in humans but are typically dependent on wound size and the presence of sepsis." (PMID 40843802, 2025). "Meanwhile, animal studies using lipopolysaccharide- or cecal ligation and puncture-induced sepsis showed that blood IL-6 levels were significantly higher in aged mice than in younger mice." (PMID 39800741, 2025). "Elevated levels of senescence-associated secretory phenotype (SASP) markers, including IL-6, IL-1β, and TNF-α, have been detected in mice subjected to cecal ligation and puncture (CLP) to induce sepsis." (PMID 40153575, 2025).